CDK2 (cyclin dependent kinase 2)
Diseases named in the same sentence as CDK2 in open-access papers (continued):
Sharing a sentence is not in itself a finding about the gene and the disease.
melanoma (continued). "Our results showed that knockdown of Piezo1 suppressed the viability of melanoma cells and decreased the expression of Cyclin D1 and CDK2." (PMID 36112948, 2022). "In fact, CDK2 has been identified as a key driver of melanoma resistance against BRAF and Hsp90 inhibitors." (PMID 36230567, 2022). "Taking into account that we have compared metastatic melanoma cell lines with different migration strengths, increased CDK2 protein level in MNT1 confirms its importance as a prognosis biomarker." (PMID 36776379, 2022). "CDK2 is shown to be dysfunctional in several malignancies, including lung cancer (cyclin A/CDK), melanoma, osteosarcoma and ovarian cancer (cyclin E/CDK2), which is usually due to overexpression of cyclin E and/or cyclin A." (PMID 35053461, 2022). "We found CDK2/4/6 expression was particularly up-regulated in melanoma, glioblastoma, breast, colon, lung adenocarcinoma, head and neck, pancreatic, liver, and prostate cancer cohorts, compared to the adjacent normal tissues." (PMID 33668805, 2021). "MITF can regulate cell cycle progression by modulating cyclin-dependent kinase-2 (CDK2), which is important for melanoma clonogenic growth." (PMID 33746605, 2021). "The results of the survival analysis of patients with melanoma in TCGA demonstrated that the high expression of CDK2, CDK4, KIT, and VWF significantly reduced the survival rate of patients." (PMID 34582363, 2021). "To examine the function of p75NTR‐FL/CTF in melanoma, we quantified the mRNA levels of cell‐cycle effectors, including cyclin‐dependent kinase 2 (CDK2), CDK4, cyclin D1, cyclin B1 and cyclin‐dependent kinase 1 (cdc2), by quantitative RT‐PCR (qRT‐PCR)." (PMID 33247998, 2021). "The results revealed a similar trend of the negative association of various immune cell infiltrations with CDK2, CDK4, and STAT3 SCNA in GBM and CDK2/4/6/STAT3 SCNA in melanoma." (PMID 33668805, 2021). "The results also showed that overexpression of miR-7013-3p significantly reduced CDK2 gene expression and inhibited proliferation in B16 melanoma cells." (PMID 33746605, 2021). "By grouping the CDK2 and CDK4 expression levels of melanoma samples, survival analysis of patients in the high- and low-expression groups showed that the high expression of CDK2 and CDK4 significantly reduced the OS rate of patients with melanoma." (PMID 34582363, 2021). "These authors suggested that proteasome-mediated degradation of Cdc25A was responsible for the reduced activity of CDK2, resulting in the G1 arrest of the melanoma cells." (PMID 33228205, 2020). "In another combination study, the resistance in melanoma patients following the use of the Hsp90 inhibitor XL888 with the BRAF inhibitor vemurafenib was reverted by the use of dinaciclib as a CDK2 inhibitor." (PMID 32397330, 2020). "Prognostic analysis results showed that high expression levels of hsa-miR-550a-3p, CDK2 and POLR2A and low expression levels of hsa-miR-150-5p in melanoma patients were associated with significantly reduced overall survival." (PMID 33313406, 2020). "In summary, HO-1 mediated B-Raf expression and then increased the expression of cyclin E/CDK2, which are involved in regulating the cell cycle and cell proliferation in melanoma." (PMID 30634993, 2019). "Most tumors, including melanoma, have an abnormal G1-to-S-phase transition, mainly due to the deregulated activity of cyclin E, cyclin D, CDK2 and CDK4." (PMID 30634993, 2019). "Mechanistic studies revealed that HO-1 was associated with a marked activation of B-RAF-ERK1/2 signaling and led to CDK2/cyclin E activation, thereby promoting melanoma proliferation." (PMID 30634993, 2019).
melanoma (continued). "In this study, differential expression analyses revealed that many genes, including AKT1 and CDK2, play important roles in melanoma." (PMID 30385854, 2019). "We observed a similar positive correlation between MITF and CDK2 in melanoma patients, where melanoma exhibited the greatest and most significant correlation (Pearson r = 0.6, Padj = 3.3 e−53) among the available cancers (Dataset EV6)." (PMID 29507054, 2018). "For the first time, it is shown that upon Hsp90i treatment melanoma upregulates MITF expression to sustain CDK2 upregulation to survive, while the MAPK pathway is inactive." (PMID 29507054, 2018). "MITF regulates the expression of numerous genes involved in the regulation of cell proliferation, such as B-cell lymphoma 2 (BCL2), cyclin-dependent kinase 2 (CDK2), cyclin D1, and p21, and promotes cell proliferation in melanocytes and melanomas." (PMID 28880216, 2017). "We have found that Les-3833 decreased the level of both Cdk2 and phosphorylated form of Rb protein in human melanoma cells of WM793 line." (PMID 28409496, 2017). "To identify miR-514a regulated targets we conducted a miR-514a-mRNA ‘pull-down’ experiment, which revealed hundreds of genes, including: CTNNB1, CDK2, MC1R, and NF1, previously associated with melanoma." (PMID 25980496, 2015). "In melanoma, the upregulation of MITF can regulate tissue-dependent regulation of CDK2 (cyclin-dependent kinase 2), which plays important role in melanoma proliferation." (PMID 26393652, 2015). "In this study, we aimed to determine the small molecules binding and inhibiting the function of CDK2 that would be an effective method to interfere with the aggressive biological behavior of advanced melanoma." (PMID 25045703, 2014). "One study has demonstrated a significant increase of cyclin E and CDK2 expression during tumor progression in malignant melanoma compared to benign melanocytic lesions." (PMID 25045703, 2014). "A recent study showed that CDK2 expression was regulated in melanoma cells by the melanocyte specific transcription factor MITF, and that CDK2 knockdown significantly reduced melanoma growth." (PMID 23527225, 2013). "It has been previously shown that MITF is critical for maintaining the expression of CDK2 in melanoma cells, and that that levels of both CDK2 and MITF predict responses to the CDK inhibitor roscotivine." (PMID 23527225, 2013). "An initial screen of our panel of melanoma cell lines identified a group of melanoma cell lines with high CDK2 expression and a group with low CDK2 expression." (PMID 23527225, 2013). "At the RNA level, there was good positive correlation between levels of CDK2 and the transcription factor MITF in both BRAF-V600E and NRAS mutated melanoma cell lines." (PMID 23527225, 2013). "It was further demonstrated that melanoma cell lines with lower expression of CDK2 were more sensitive to the cyclin-dependent inhibitor roscovitine." (PMID 23527225, 2013). "The ability of dinaciclib to induce apoptosis in the melanoma cell line panel was unrelated to either CDK2 expression levels or BRAF/NRAS mutational status, suggesting that this drug had broad-spectrum anti-melanoma activity." (PMID 23527225, 2013). "After screening a large panel of melanoma cell lines, we identified 5 melanoma cell lines that expressed high levels of CDK2 mRNA (CDK2 HIGH) and 6 that expressed low levels of CDK2 mRNA (CDK2 LOW)." (PMID 23527225, 2013). "A tight correlation has been observed between MITF and CDK2 expression levels in primary melanoma specimens and several melanoma cell lines." (PMID 22848417, 2012).
melanoma (continued). "Recently, it has been reported that NFV induces anchorage-independent growth and a G1 cell cycle arrest in melanoma cells by decreased activity of CDK2, a master kinase that regulates G1-S progression." (PMID 20701796, 2010). "MiTF also controls the expression of Tbx2 and CDK2, which are involved in melanoma proliferation and suppression of senescence, in addition to anti-apoptotic genes such as Bcl2 and ML-IAP." (PMID 20174581, 2010). "Despite all the evidence suggesting that MITF must be down-regulated for melanoma progression, MITF expression is essential for proliferation and survival of melanoma cells because it regulates genes such as CDK2 and BCL-2 respectively." (PMID 18628967, 2008). "Critically, in melanoma cells MITF is required downstream of oncogenic BRAF because it regulates expression of key cell cycle regulatory proteins such as CDK2 and CDK4." (PMID 18628967, 2008). "Additionally, our examination showed that CDK2, GSK3B, CSNK2A1, and CDK1 were the significant kinases that target the greatest number of genes associated with metastatic-melanoma." (PMID 39820173, 2025). "On the other hand, proliferation-related genes, including cdk2, minichromosome maintenance complex component 7 (mcm7), pcna, marker of proliferation Ki-67 (mki67), and cdk1 were upregulated in the melanoma tissues while being unaltered in nevi, when compared to the control." (PMID 38020918, 2023). "The research suggests that targeting CDK2 could suppress melanoma cell growth, induce apoptosis, and overcome melanoma resistance." (PMID 37120608, 2023). "Similarly, analysis of the melanoma TCGA dataset revealed that GREB1 gene expression was positively correlated with the expression of proliferative marker genes (CDK2, MYC, CCND1, and LIG1) and negatively correlated with CDKN1B." (PMID 37658191, 2023). "These outcomes endorsed that the most active candidates 5c and 8a may serve as useful lead compounds in the search for promising anti-melanoma agents acting through CDK2 inhibition." (PMID 35139719, 2022). "The western blotting results showed that the protein levels of cyclins such as cyclin E1 and CDK2 were increased in PRPS1-overexpressing melanoma cells, while the level of P16 was decreased compared with the control group, while the opposite was true in PRPS1 knockdown A875 and SK-MEL-110 cells." (PMID 36203561, 2022). "MITF regulates CDK2 in melanoma, which is critical for tumor cell growth." (PMID 36551682, 2022). "We also found a negative association of CDK2/4/6/STAT3 SCNA with the various immune infiltration in melanoma." (PMID 33668805, 2021). "Targeting CDK2 overcomes melanoma resistance against Hsp-90 and BRAF inhibitors." (PMID 33805800, 2021). "Previous data revealed that the inhibition of CDK2 could significantly reduce the growth of melanoma cells." (PMID 29684087, 2018). "Conversely, knocking down of MCL1 in melanoma cells increased the ubiquitinated CDK2." (PMID 29072681, 2017). "We surveyed kinome expression patterns across sub-populations of the BRAF/NRAS wild type sample and found that CDK4 and CDK2 were consistently highly expressed in the majority of cells, suggesting that these kinases might be involved in melanoma progression." (PMID 27903987, 2017). "Moreover, we show that the suppression of NAT10 reduces melanoma growth with abnormal expression of cell cycle-regulating genes such as CDK2 and cyclin D1 in vitro and in vivo." (PMID 28880216, 2017). "Moreover, the suppression of cyclin D1 and cyclin E by CoQ0 led to the inhibition of CDK4 and CDK2 levels in melanoma cells." (PMID 26968952, 2016).
melanoma (continued). "Wellbrock and coworkers proposed that a low basal MITF level could be important for the survival of melanoma cells and also for their proliferation through regulation of cyclin-dependent kinase 2 (CDK2) and B-cell CLL/lymphoma 2 (BCL2)." (PMID 26927636, 2016). "Furthermore, six SNPs in TYR, SILV/CDK2, GPR143, and F2RL1 showed strong differences in melanoma risk by sex (P < 0.01)." (PMID 26998216, 2016). "However, in melanoma cells we observed a cell-cycle arrest as initial response, which confirms previous findings of nelfinavir inducing a G1 arrest and suppressing CDK2 activity in melanoma cells." (PMID 26977879, 2016). "Cyclin-dependent kinase 2 (CDK2) is a unique target among the CDK family in melanoma therapy." (PMID 25045703, 2014). "CDK2 is a unique target among the CDK family in melanoma therapy." (PMID 25045703, 2014). "Inhibition of CDK2 significantly reduced growth of melanoma cells." (PMID 25045703, 2014). "All of them had the ability to inhibit the activity of CDK2 and might have the opportunity to be used in melanoma therapy." (PMID 25045703, 2014). "All of them had the ability to inhibit the activity of CDK2 and might have the opportunity to be applied in melanoma therapy." (PMID 25045703, 2014). "CDK2 has an important role in the occurrence and progression of melanoma among its CDK family." (PMID 25045703, 2014). "Previous work has shown that melanoma sub-groups exist with either high or low expression levels of CDK2, with the low CDK2 expressing cell lines posited to be the optimal group for receiving CDK2 inhibitor therapy." (PMID 23527225, 2013). "Among the CDK family, CDK2 has a unique role in the development and progression of melanoma." (PMID 23527225, 2013). "Although cyclin dependent kinase (CDK)-2 is known to be dispensable for the growth of most tumors, it is thought to be important for the proliferation of melanoma cells, where its expression is controlled by the melanocyte-lineage specific transcription factor MITF." (PMID 23527225, 2013). "Regulation of CDK2 by MITF is essential for melanoma clonogenic growth." (PMID 22848417, 2012). "Moreover, YTHDF1 or HNRNPA2B1 might interact with RNA processing-related genes such as CDK1/CDK2 and further promote the formation and progression of melanoma." (PMID 32549786, 2020). "This is most likely because in melanoma invasion reflects in part a response to a low nutrient supply environment and that by promoting proliferation, for example by activating CDK2, MITF imposes a high nutrient demand state that is incompatible with nutrient limitation." (PMID 31207090, 2019). "Moreover, CDK2 depletion suppresses cell cycle progression in melanoma cells." (PMID 30634993, 2019). "In anti-melanomas compounds, we have demonstrated that alternol could decrease the expression levels of cyclin-dependent kinase 2 (CDK2) and proliferating cell nuclear antigen (PCNA), and activate CDK inhibitor1A (p21) to inhibit melanoma B16F0 cell proliferation." (PMID 27796318, 2016). "Besides melanoma, CDK2 is also overexpressed in other tumors." (PMID 25045703, 2014). "As all of the melanoma lines tested responded to treatment in a similar manner in the in vitro assays, we chose to perform the mouse xenograft experiments with the WM1366 cell line (CDK2 low/NRAS mutated) to assess if the compound would still be effective if CDK2 levels were low." (PMID 23527225, 2013).
melanoma (continued). "Through literature mining, it was found that the four known melanoma-related proteins PIM1, MEK1, CDK2, and PDK1 can potentially be targets of the bioactive compounds of B. stenostachya." (PMID 40649898, 2025). "CDK1, or cyclin-dependent kinase, is involved in the control of cell proliferation and cycle, and similar to CDK2, overexpression of CDK1 has been revealed in multiple malignancies, such as metastatic-melanoma." (PMID 39820173, 2025). "The pathway enrichment analysis revealed the four melanoma-related proteins PIM1, MEK1, CDK2, and PDK1 in several pathways including the pathways related to cancer." (PMID 40649898, 2025). "Honokiol inhibited melanoma growth and metastasis, induced CHOP activation in ER stress, and reduced the expression of MITF, β-catenin, and CDK2 in melanoma tissues (in vitro, in vivo)." (PMID 40943669, 2025). "Together, these findings validate the biological relevance of the added proteins, namely PIM1, MEK1, CDK2, and PDK1, in the central pathways of melanoma." (PMID 40649898, 2025). "To evaluate the effects of CDK4/6 and CDK2 inhibitors on the cell cycle of B16F10 and 1014 melanoma cells, we chose a 24-hour treatment time to ensure capture of early and drug-specific effects." (PMID 40904502, 2025). "Knockout and gene silencing of RSK family members had an overall minimal or insignificant effect on the proliferation of melanoma cell lines, whereas the targeting of PLK1 had a dramatic effect, followed by the targeting of Aurora B, FAK, and CDK2." (PMID 39658088, 2025). "It is significant that the average docking scores for naringin-7-rhamnoglucoside and the melanoma-related proteins were as follows: PIM1 (−5.91897), MEK1 (−6.07004), CDK2 (−5.26133), and PDK1 (−6.29952)." (PMID 40649898, 2025). "Our results show that optimal inhibition of tumor growth in the B16F10 melanoma model can be obtained with co-inhibition of CDK4/6 and CDK2 along with SX-682." (PMID 40904502, 2025). "In light of these findings, it becomes clear that melanoma cells exploit a diverse range of pathways which can be targeted by the bioactive compounds of B. stenostachya, particularly PIM1, MEK1, CDK2, and PDK1." (PMID 40649898, 2025). "MC extract administration induced the amelioration of melanoma by controlling the PAX3/PTEM/PIP3/Akt/mTORC1 and PAX3/MITF/CDK2·c-Met·Bcl2·RAB27A signaling pathways, which are involved in melanoma proliferation and invasion." (PMID 39684511, 2024). "The MC extract also decreased the expression of MITF, CDK2, c-Met, Bcl2, and RAB27A, which had increased with melanoma cell treatment." (PMID 39684511, 2024). "Mutated BRAF exerts exquisite control over MITF, which regulates the expression of key cell cycle facilitators, such as CDK2 and CDK4, stimulating melanoma cell proliferation, survival, and phenotype switching from proliferative and invasive states." (PMID 39735251, 2024). "In the current study, melanoma cell treatment increased the expression of MITF and its downstream genes CDK2, c-Met, Bcl2, and RAB27A." (PMID 39684511, 2024). "By intersecting the key cluster and the intersection of drug-related genes and melanoma-related genes, we finally identified three crucial targets, EGFR, ERBB2, and CDK2, which are all protein serine/threonine kinases and are involved in cell cycle regulation." (PMID 38348352, 2023). "Collagen stiffness induced the expression of melanoma differentiation genes TRPM1, PMEL, TYR and MLANA, as well as well as the proliferation and survival genes CDK2 and BCL2A1." (PMID 36135194, 2022). "PHA-793887 is an inhibitor of multiple cyclin-dependent kinases (CDKs), with activity against CDK2, CDK1, and CDK4, and has been validated to enhance immunotherapy against melanoma." (PMID 35680563, 2022). "THP is effective in treating melanoma by inhibiting the activity of CDK2, which is a unique target among the CDK family members in melanoma therapy." (PMID 35559252, 2022).